INS (insulin)
Diseases named in the same sentence as INS in open-access papers (continued):
Sharing a sentence is not in itself a finding about the gene and the disease.
Insulin resistance (continued). "Research has shown that the phenolic acids in MEHHs may prevent and ameliorate disorders in glucose and lipid metabolism by modulating glucose and lipid metabolism, insulin signaling, reducing insulin resistance, curtailing inflammation and oxidative stress, and regulating gut flora." (PMID 39459158, 2024). "The association between higher BMI and higher HbA1c may be explained by insulin resistance secondary to excess adiposity, and subsequent need for greater insulin doses to maintain ideal glycemia.4‐6 Higher insulin doses increase treatment complexity, and may impact glycemic stability." (PMID 38799027, 2024). "Furthermore, this oxidative stress and persistent inflammation can feed into each other, enhancing hyperglycemia and insulin resistance through various mechanisms, including the disruption of insulin signal transduction (IST) and the enhancement of β-cell and mitochondrial dysfunction." (PMID 38671903, 2024). "Additionally, we observed that insulin levels were temporarily increased at the prediabetic stage in HFHSD male mice while glucose concentrations continued to rise to diabetic levels, suggesting increased insulin levels lead to insulin resistance in males as well." (PMID 39337631, 2024). "Therefore, in many cases, while a true diagnosis of insulin resistance may be helpful, monitoring resting insulin concentrations can be a good management tool for owners and veterinarians to help identify horses that might be at risk of developing laminitis." (PMID 38473112, 2024). "Therefore, insulin resistance, followed by increase in insulin secretion may in turn affect T cell activity, contributing to a vicious state of persistent T cell activation and potentially T cell exhaustion." (PMID 39641064, 2024). "Also, insulin resistance in T1DM may be related to how therapeutic exogenous insulin is administered." (PMID 39768947, 2024). "This is because as T2DM progresses, patients often experience increased insulin resistance, pancreatic β-cells may fail to secrete adequate insulin, and poor self-care activities, including inadequate diet and lack of physical activity, can lead to poor glycemic control." (PMID 39633380, 2024). "Furthermore, its role in glucose metabolism and insulin secretion may exacerbate insulin resistance in PCOS patients, especially when combined with disordered eating behaviors." (PMID 39797110, 2024). "Recently, in the search for new drugs to inhibit pro-inflammatory adipokine secretion in type 2 diabetes patients, emerging evidence has identified that the CXCR1/2 inhibitor ladarixin could enhance insulin resistance in 3T3-L1 adipocytes by reducing inflammation and improving insulin signaling." (PMID 38989000, 2024). "In addition to modulating abnormally active immune system, hMSCs can ameliorate peripheral insulin resistance, halt beta-cell destruction, preserve residual beta-cell mass, promote beta-cell regeneration and insulin production, support islet grafts, and correct lipid metabolism." (PMID 39468609, 2024). "Interestingly, ITT showed that insulin resistance was lower in the group with FO and vit D compared to the other groups, indicating that the combination improved insulin sensitivity, which may be due to their predominant activity in adipose tissue and muscle." (PMID 38672490, 2024). "Dysfunction of mitochondrial FA β-oxidation due to insulin resistance further induces mitochondrial oxidative stress, endoplasmic reticulum (ER) stress, and inflammatory responses, which, in turn, aggravates insulin resistance in hepatocytes by blunting the insulin signalling cascade." (PMID 39872125, 2024). "However, insulin resistance tends to worsen over time, and beta cells’ insulin production may gradually deteriorate." (PMID 39768947, 2024).
Insulin resistance (continued). "A novel finding in this study is the significant inverse association between fasting plasma insulin or insulin resistance and hippocampal tail in non-diabetic FEP patients, at the one-year follow-up time point, independent of antipsychotic and antidepressant medications." (PMID 39085221, 2024). "Since insulin resistance was an initial abnormality in the development of T2D, relationship between periodontitis and FI, the biochemical parameters that reflected the β-cell insulin production and insulin resistance, was further analyzed to confirm the conclusion." (PMID 38811930, 2024). "Specifically, insulin-sensitizing agents and inhibitors of insulin-like growth factor-1 receptor (IGF-1R) have been investigated as potential treatments for lung cancer, aiming to inhibit aberrant signaling and cell proliferation associated with insulin resistance." (PMID 38449844, 2024). "Characterized by hyperglycemia and elevated insulin levels, insulin resistance promotes the interaction between insulin and insulin-like growth factor binding proteins (IGFBPs), increasing free IGF-1 levels, This, in turn, may influence cellular regulation and proliferation within thyroid tissue." (PMID 39444449, 2024). "Therefore, blood glucose and HOMA scores may be more valuable in reflecting prediabetes or insulin resistance than insulin level alone." (PMID 38503991, 2024). "Insulin resistance may be the first consideration as the reason for this association, because it was putative as the pathogenesis of HDP and GDM in pregnant women, and cord plasma insulin correlated positively with birthweight and neonatal fat mass." (PMID 39726848, 2024). "As skeletal muscle insulin resistance is a central and early defect in the pathogenesis of type 2 diabetes, detailed knowledge of the factors regulating insulin action in muscle is important and may provide novel insight into improving treatment of people with insulin resistance." (PMID 38814443, 2024). "Hyperandrogenemia resulting from elevated insulin levels contributes to excessive keratinocyte proliferation of the pilosebacious unit of hair follicles, which may account for the increased incidence of keratosis pilaris in individuals with insulin resistance." (PMID 38398863, 2024). "In a study on the contribution of TNFα to insulin resistance (IR), the authors compared the transcriptional profiles of rat H‐411E hepatocytes exposed to insulin with or without TNFα, in which Gadd45β expression was upregulated by insulin and then reversed by TNFα." (PMID 39653679, 2024). "However, data are lacking on whether that degree of pregestational BMI is related to insulin resistance or the need for insulin treatment after pregnancy." (PMID 39803116, 2024). "Hence, supporting our hypothesis, QG may serve as a drug to alleviate insulin resistance through the activation of insulin-Akt signaling." (PMID 38474775, 2024). "Furthermore, a meta-analysis of seven eligible trials involving 503 participants with hyperuricemia demonstrated that urate-lowering therapy led to decreases in systolic and diastolic blood pressure, fasting insulin levels, and homeostasis model assessment of insulin resistance." (PMID 38380182, 2024). "Indeed, it has been posited that an excessive intake of iron through the diet in pregnant women with ample iron reserves can heighten oxidative stress, which leads to insulin resistance and an insufficient compensatory maternal insulin response, resulting in fetal hyperglycemia and hyperinsulinemia." (PMID 38337721, 2024). "In addition, daily supplementation of 20-hydroxyecdysone (at a dose of 10 mg/Kg) to diet-induced obesity and insulin resistance C57BL/6 J rats for 13 weeks significantly reduced plasma insulin levels and glucose tolerance, as well as body weight and fat mass in obese rats." (PMID 39430786, 2024). "The dominant defect may be excess insulin resistance, insufficient insulin secretion, or both." (PMID 39083240, 2024).
Insulin resistance (continued). "Thus, adjustments for insulin secretion could be useful for the assessment of insulin resistance and sensitivity with HOMA-IR and the Matsuda Index in AAb+ relatives." (PMID 37914981, 2024). "There was a trend of negative association between fasting plasma insulin or insulin resistance and hippocampal tail, but also between fasting plasma insulin or insulin resistance and total hippocampal volume at the follow-up time point of CHR converted to psychosis." (PMID 39085221, 2024). "Insulin resistance induced by lipids, according to the DAG hypothesis, suggests the interference of intracellular insulin signaling associated with the activation of protein kinase C (PKC) due to the accumulation of diacylglycerol within insulin-sensitive tissues." (PMID 38397072, 2024). "Similarly, research in obesity and other insulin-resistant phenotypes suggests a decline in the capillary network of skeletal muscles and impaired insulin-mediated capillary recruitment, both leading to insulin resistance and impairing glucose uptake." (PMID 37902457, 2024). "Similarly, elevated tyrosylvaline might contribute to insulin resistance by affecting insulin signaling pathways." (PMID 39195507, 2024). "Thus, clinical research employing a more sensitive assessment of insulin clearance is needed to determine in human subjects that reduced insulin clearance can cause insulin resistance and is not just a consequence thereof." (PMID 39640841, 2024). "IFNγ-producing NK cells in AT are associated with hyperglycaemia and insulin resistance in obese women, while a deficiency of NK cells or IFN-γ was shown to prevent the accumulation of pro-inflammatory macrophages in VAT and greatly ameliorate insulin sensitivity." (PMID 38334487, 2024). "The use of these chemicals in T2DM research might seem counterintuitive since T2DM is typically characterized by insulin resistance followed by a relative, rather than absolute, deficiency in insulin secretion." (PMID 38444587, 2024). "Additionally, in disease conditions that involve impaired insulin sensitivity and increased insulin resistance, the activity of insulin at the skeletal muscle level is altered, reducing the skeletal muscle glucose intake, glycogenic pathways, and muscle cell energy substrate (ATP) levels." (PMID 39433511, 2024). "To further establish glycolysis as a regulator of insulin responsiveness in skeletal muscle, we decided to investigate whether upregulating glycolysis through F2,6BP production can restore insulin-stimulated glucose uptake in insulin resistance." (PMID 38329473, 2024). "Therefore, by concurrently addressing both hyperglycemia and insulin resistance, combination therapy with hydrocortisone and insulin may offer synergistic effects in improving glycemic control and ameliorating the metabolic derangements associated with DS." (PMID 38773407, 2024). "However, in patients with IGT and T2D, increased insulin resistance is not adequately balanced by increased insulin secretion, indicating a relative insulin deficiency." (PMID 38550917, 2024). "In conclusion, this study used the novel approach of adjusting for insulin secretion in assessing whether insulin resistance and insulin sensitivity, indicated by HOMA-IR and the Matsuda Index, respectively, are factors involved in the progression towards type 1 diabetes." (PMID 37914981, 2024). "Moreover, elevated liver enzyme levels are biomarkers of increased insulin resistance and decreased insulin sensitivity, which may lead to postprandial hyperglycemia." (PMID 38836232, 2024). "However, neither fasting insulin levels nor the homeostasis model assessment for insulin resistance showed significant associations with the risk of stroke or its subtypes in this non-diabetic elderly population." (PMID 39347227, 2024). "Furthermore, drugs that can modulate insulin resistance, such as insulin sensitizers and anti-inflammatory agents, may also hold promise in the treatment of lung cancer." (PMID 38449844, 2024).
Insulin resistance (continued). "Additionally, they directly counteract insulin signal transduction, leading to insulin resistance." (PMID 38774257, 2024). "Indeed, PKC’s purported role in dysregulating insulin signalling through inhibition of the phosphatidylinositol 3-kinase (PI3K)/Akt pathway may suggest a role for sphingosine in ameliorating cellular insulin resistance phenotypes." (PMID 39408263, 2024). "Leaky gut syndrome (LGS) may be caused by HFD, leading to MP deposition in the intestinal mucosa, causing inflammation of the inner layer of the intestinal mucosa, exacerbating insulin resistance and affecting insulin secretion, thereby affecting the blood glucose levels." (PMID 39330511, 2024). "As one of the hallmarks of insulin resistance is impaired glycogen synthesis in skeletal muscle during in vivo insulin stimulation, our observation that roxadustat treatment enhanced insulin action on glycogen synthesis in myotubes from donors with type 2 diabetes is exciting." (PMID 38814443, 2024). "The O-MAINT cats in the present study did not present with clinical signs for hepatic lipidosis or insulin resistance; however, increased serum BHB and insulin was observed which could indicate greater propensity for insulin resistance in the O-MAINT cats, though this cannot be confirmed." (PMID 38489282, 2024). "T2DM is caused by a relative lack of insulin production in tissues and insulin resistance." (PMID 38952685, 2024). "Estrogen contributes to insulin sensitivity by regulating insulin secretion and delivery, suppressing hepatic glucose production, improving glucose homeostasis in insulin-sensitive tissues, and suppressing inflammation and oxidative stress to protect against insulin resistance." (PMID 40988882, 2024). "While phosphorylation of IRS1 at S307 has been linked to insulin resistance, whether it is part of a negative or positive feedback loop that controls insulin signaling remains controversial and could be tissue-dependent." (PMID 38029396, 2024). "High intake of dietary fats, associated with elevated triacylglycerides, may have also contributed to the development of insulin resistance as it has been observed that increased exposure of triacylglycerides to insulin-dependent peripheral tissues induces insulin resistance." (PMID 38612885, 2024). "Moreover, excessive lipids in the liver will further impair the insulin signaling pathway, aggravating insulin resistance and exacerbating dysregulation in lipid metabolism, notably marked by elevated triglycerides and LDL-cholesterol levels, and lowered HDL-cholesterol levels in circulation." (PMID 39337412, 2024). "Moreover, there is evidence that the FokI polymorphism (the main mediator of vitamin D action) may affect insulin secretion and insulin resistance." (PMID 38812030, 2024). "In addition, nutritional ketosis protects against the potentially detrimental effects of insulin resistance, high levels of insulin, and high/variable levels of glucose, thereby probably preventing and even treating symptoms of psychiatric disease and neurodegeneration." (PMID 39539363, 2024). "Moreover, saturated fat is a known antagonist of insulin and a contributor to insulin resistance." (PMID 38446775, 2024). "Indeed, animal and cell studies have shown that SFAs, Palmitate, in particular, directly upregulates de-novo ceramide synthesis and immune signalling activation, possibly via activation of the TLR4, and indirectly compromises insulin signalling to promote insulin resistance." (PMID 39408263, 2024). "Additionally, insulin signaling pathway elements, as markers of insulin resistance, were assessed." (PMID 39830652, 2024). "The assessment of the disposition index could help to clarify to what extent the association with insulin secretion is independent of insulin resistance." (PMID 37831076, 2024). "Moreover, LPL activity in skeletal muscle negatively correlates with plasma insulin levels and could be lowered by insulin resistance." (PMID 38674801, 2024).
Insulin resistance (continued). "Notably, the high expression of SREBF1 postpartum induced by insulin supplementation may serve as a key point to relieve insulin resistance, lower NEFA concentrations in obese cows." (PMID 39881718, 2024). "However, metabolic stress such as insulin resistance requires increased insulin secretion." (PMID 38999937, 2024). "Additionally, LPS may disrupt the insulin signaling pathway, leading to insulin resistance at the cellular level, thereby elevating blood glucose levels and contributing to the progression of MAFLD." (PMID 38396863, 2024). "Furthermore, research has identified that reduced cortisol levels in mice exposed to 55 μg/d microplastics might interfere with insulin secretion, thereby inducing insulin resistance." (PMID 38251002, 2024). "Similarly, brain insulin resistance is the inability of brain cells to respond to insulin." (PMID 38913047, 2024). "Interestingly, the relationship between fasting insulin levels and BMD varied based on the insulin resistance level, while a low insulin resistance showed a positive association, higher insulin resistance correlated with reduced BMD, with significance increasing with insulin resistance severity." (PMID 39765929, 2024). "However, a long-term regime of insulin injection may lead to insulin resistance, which may aggravate T2DM symptoms." (PMID 39125375, 2024). "Because maintaining low insulin and reducing insulin spikes have been shown to reduce the incidence of insulin resistance, and its many deleterious downstream health effects, a LC/HF shake could be a useful means of breaking a fast and extending some of the metabolic benefits." (PMID 38201992, 2024). "However, obesity leads to a progressive defect in insulin secretion and enhances insulin resistance, which could further strengthen the development of obesity." (PMID 39590824, 2024). "Finally, we confirmed the role of glycolysis in modulating insulin action in insulin resistance." (PMID 38329473, 2024). "However, the same study showed a strong association between elevated iron markers and insulin resistance, which supports the link between iron metabolism and insulin metabolism, rather than suggesting age as the primary driver of our findings." (PMID 40895225, 2024). "It is still unclear whether obesity itself or the often associated whole-body insulin resistance is responsible, as there are no studies on brain insulin action in individuals who are obese but still insulin sensitive." (PMID 38363340, 2024). "Reduced vascular nitric oxide (NO) generation and decreased insulin-induced vasodilation are symbols of insulin resistance, and both conditions might result in vascular endothelial dysfunction, a significant pathophysiological process that underlies erectile dysfunction." (PMID 38741154, 2024). "Furthermore, vitamin D levels might improve insulin resistance, promote insulin production, and regulate lipid metabolism, thereby reducing kidney damage." (PMID 39185464, 2024). "The explanation for this phenomenon may be that insulin induced glucose uptake occurs in skeletal muscle, and high muscle mass can stabilize the control of glucose levels, providing a certain protective effect on insulin resistance and MetS46,47." (PMID 38702424, 2024). "At the same time, activation of PI3K inhibits the activity of c-Jun N-terminal kinase 1 (JNK1), an enzyme associated with cellular stress response and inflammation, and its overactivation may interfere with insulin signaling pathways, leading to insulin resistance." (PMID 39596859, 2024). "Insulin resistance (IR) is a pathological condition in which insulin promotes reduced glucose uptake and utilization due to environmental and genetic variations, resulting in reduced sensitivity and responsiveness of the body to the physiological effects of insulin." (PMID 39138413, 2024).